ITGA2B (integrin subunit alpha 2b)
Description:
Integrin alpha-IIb/beta-3 (ITGA2B:ITGB3) is a receptor for fibronectin, fibrinogen, plasminogen, prothrombin, thrombospondin and vitronectin. It recognizes the sequence R-G-D in a wide array of ligands. It recognizes the sequence H-H-L-G-G-G-A-K-Q-A-G-D-V in fibrinogen gamma chain (By similarity). Following activation integrin alpha-IIb/beta-3 brings about platelet/platelet interaction through binding of soluble fibrinogen. This step leads to rapid platelet aggregation which physically plugs ruptured endothelial cell surface (By similarity). Integrin ITGA2B:ITGB3 is also the receptor of erythrocyte-specific ICAM4 ligand involved in heterotypic cell-cell adhesion between erythrocytes and activated platelets.
Synonyms: GPIIb; CD41; GP2B; CD41B; PPP1R93; BDPLT16; BDPLT2; FMAIT2; GT; GT1; GTA; HPA3
Tractability: Small molecule: an approved drug acts on it; a structure with a bound ligand is known; a high-quality ligand is known; it has a high-quality binding pocket; it belongs to a druggable protein family. Antibody: a drug acting on it is in phase 2 or 3 trials; its Gene Ontology location is reachable by antibodies, with high confidence; UniProt predicts a signal peptide or a membrane-spanning region; the Human Protein Atlas places it where antibodies can reach. PROTAC: its protein half-life has been measured; a small molecule that binds it is known. Other modalities: an approved drug acts on it.
Target class: Membrane receptor
Gene: Protein-coding gene on chromosome 17 (44,372,177 to 44,389,649, reverse strand). Ensembl gene ENSG00000005961.
Subcellular location: Cell membrane
Subcellular location (Human Protein Atlas): Plasma membrane
Pathways (Reactome):
Disease: Paradoxical activation of RAF signaling by kinase inactive BRAF; Signaling by BRAF and RAF1 fusions; Signaling by RAF1 mutants; Signaling by high-kinase activity BRAF mutants; Signaling by moderate kinase activity BRAF mutants; Signaling downstream of RAS mutants
Signal Transduction: GRB2:SOS provides linkage to MAPK signaling for Integrins; Integrin signaling; MAP2K and MAPK activation; p130Cas linkage to MAPK signaling for integrins
Extracellular matrix organization: ECM proteoglycans; Integrin cell surface interactions
Hemostasis: Fibrin formation; Platelet degranulation
Developmental Biology: Signal transduction by L1
Gene expression (Transcription): RUNX1 regulates genes involved in megakaryocyte differentiation and platelet function
Gene Ontology:
Molecular function: cell adhesion receptor activity; identical protein binding; molecular adaptor activity; protein binding; signaling receptor activity; extracellular matrix binding; fibrinogen binding
Biological process: cell-cell adhesion mediated by integrin; heterotypic cell-cell adhesion; integrin-mediated signaling pathway; angiogenesis; cell-cell adhesion; cell-matrix adhesion; cell adhesion; positive regulation of leukocyte migration
Cellular component: blood microparticle; cell surface; extracellular exosome; integrin alphaIIb-beta3 complex; plasma membrane; platelet alpha granule membrane; external side of plasma membrane; focal adhesion; integrin complex
Genetic constraint (gnomAD): Loss-of-function variants: 91 observed, 141.9 expected, observed/expected ratio (o/e) 0.64, 90% interval 0.54 to 0.76. The upper end of that interval is the gene's LOEUF score, 0.76, which puts it in group 3 of 6, group 1 being the genes least tolerant of losing a copy. Missense variants: 1,231 observed, 1,365.8 expected, observed/expected ratio (o/e) 0.9, 90% interval 0.86 to 0.94. Synonymous variants: 536 observed, 572.93 expected, observed/expected ratio (o/e) 0.94, 90% interval 0.87 to 1.
Gene-disease validity (ClinGen):
ClinGen rates the evidence that ITGA2B causes each of these diseases.
Glanzmann thrombasthenia (autosomal recessive): Definitive.
platelet-type bleeding disorder 16 (autosomal dominant): Definitive.
Homologues: Orthologues: macaque ITGA2B (97% identical), chimpanzee ITGA2B (93% identical), dog ITGA2B (83% identical), mouse Itga2b (80% identical), pig ITGA2B (79% identical), rat Itga2b (78% identical), rabbit ITGA2B (78% identical), guinea pig ITGA2B (73% identical), tropical clawed frog itga2b (45% identical), zebrafish itga2b (41% identical), Caenorhabditis elegans pat-2 (27% identical), Drosophila melanogaster mew (25% identical), and 5 more. Paralogues in human: ITGA8 (39% identical), ITGAV (37% identical), ITGA5 (36% identical), ITGA7 (25% identical), ITGA3 (24% identical), ITGA6 (24% identical), ITGA4 (23% identical), ITGA9 (22% identical), ITGAX (21% identical), ITGAD (21% identical), ITGA10 (21% identical), ITGAM (21% identical), and 5 more.
Diseases named in the same sentence as ITGA2B in open-access papers:
ITGA2B is named in the same sentence as 205 diseases in open-access papers, as found by Europe PMC text mining. Sharing a sentence is not in itself a finding about the gene and the disease. The quoted sentences say what the papers report.
Thrombocytopenia (55 papers, 2009 to 2025). A reduction in the number of circulating thrombocytes. "The pathogenetic c.3076C>T (p.Arg1026Trp) mutation in the ITGA2B gene was detected in one patient with a mild thrombocytopenia (median platelet count: 90 × 109/L) and hemorrhagic phenotype (bleeding score: 1)." (PMID 36507135, 2022). "The pathogenetic c.175°C>T (p.Arg584*) mutation in the ITGA2B gene was detected in one patient (52-I) with a moderate thrombocytopenia (median platelet count: 18 × 109/L) and with significant bleeding episodes (bleeding score: 2)." (PMID 36507135, 2022). "Previously reported ITGA2B and ITGB3 variants related to thrombocytopenia were clustered in a confined region of the membrane-proximal cytoplasmic domains, the inner membrane clasp." (PMID 33276370, 2020). "Genetic defects identified in the different families with thrombocytopenia, affecting the ITGA2B or the ITGB3 genes." (PMID 33276370, 2020). "These cases have deserved the designation of GT-like syndrome (GTLS) or ITGA2B/ITGB3-related thrombocytopenia (ITGA2B/ITGB3-RT)." (PMID 33276370, 2020). "In addition, deficiency or reduction of the major platelet membrane GPIb-IX and GPIIb/IIIa also cause macrothrombocytopenia named Bernard–Soulier syndrome (BSS) and ITGA2B/ITGB3-related thrombocytopenia, respectively." (PMID 34657146, 2021). "Rare pathogenic variants in either the ITGA2B or ITGB3 genes have been linked to autosomal dominant macrothrombocytopenia associated with abnormal platelet production and function, deserving the designation of Glanzmann Thrombasthenia-Like Syndrome (GTLS) or ITGA2B/ITGB3-related thrombocytopenia." (PMID 33276370, 2020). "Among the common DEPs in this pathway, CD41 (ITGA2B) and Rab27b (RAB27B) were selectively reduced in patients with WAS, likely reflecting thrombocytopenia." (PMID 39453496, 2024). "We found eight proteins (ITGA2B, ITGB3, VWF, PLEK, TNF, TLR2, BCL2 and BCL2L1) were the core targets of DMAG for the treatment of thrombocytopenia." (PMID 34837956, 2021). "Similarly, while the mutations of platelet genes Itga2b and Nfe2 confer PDA in mice but not humans, thrombocytopenia and various platelet indices correlate with PDA in preterm infants." (PMID 34350653, 2022). "The lower integrin α2b and β3 (ITGA2B, ITGB3) protein levels found in the MLL-r samples is consistent with the presumed BM microenvironment origin of these proteins: they would be expected to be present at lower levels in the BM of leukemia cases, which typically present with thrombocytopenia." (PMID 34646384, 2021).
Glanzmann thrombasthenia (49 papers, 2009 to 2026). "Glanzmann thrombasthenia (GT) is a rare, autosomal recessive platelet aggregation disorder caused by mutations in the ITGA2B and ITGB3 genes." (PMID 41798562, 2026). "Glanzmann thrombasthenia (GT) is an autosomal recessive platelet functional bleeding disorder caused by mutations in the ITGA2B or ITGB3 genes, often presenting as mucocutaneous bleeding." (PMID 39776701, 2024). "The phenotype and genotype of a pedigree with Glanzmann thrombasthenia caused by compound heterozygous mutation in the ITGA2B gene and its molecular pathogenesis were explored." (PMID 38951065, 2024). "Here, we present the case of a 40-year-old woman with Glanzmann Thrombasthenia caused by a novel likely pathogenic variant in the αIIb-subunit encoding gene ITGA2B and platelet alloantibody formation, who also suffered from intracranial aneurysms." (PMID 39057107, 2024). "The compound heterozygous mutation c.480C>G in exon 4 and c.2929C>T in exon 28 of the ITGA2B gene probably underlies Glanzmann thrombasthenia in this pedigree." (PMID 38951065, 2024). "Glanzmann thrombasthenia is caused by mutations in either the GP2B (ITGA2B) or GP3A (ITGB3) gene, and at least 100 mutations have been described and collected in an online database." (PMID 33274150, 2020). "Defects in the ITGA2B gene cause Glanzmann thrombasthenia, an autosomal recessive bleeding disorder characterized by failure of platelet aggregation and by absent or diminished clot retraction." (PMID 26910538, 2016). "While ITGA2B (integrin alpha 2b; CD41) mutations cause Glanzmann thrombasthenia, activation of the glycoproteins IIb/IIIa complex triggered by conformational changes plays a central role in thrombus formation and acute myocardial infarction." (PMID 27439789, 2016). "Glanzmann thrombasthenia (GT) is an autosomal recessive platelet disorder caused by mutations in the ITGA2B or ITGB3 genes encoding the plasma membrane glycoproteins αIIb (GPIIb, CD41) and β3 (GPIIIa, CD61), respectively." (PMID 25607928, 2015). "Mutations of Itga2b and Itgb3 are assoicated with Glanzmann thrombasthenia, the most common inherited disease of platelet function in humans, causing a bleeding disorder." (PMID 24147020, 2013). "For instance, in Glanzmann thrombasthenia, an autosomal recessive genetic disease, asymptomatic carriers who are heterozygous for the causative gene (ITGA2B or ITGB3) tend to have a lower expression of integrin glycoprotein IIb-IIIa on the platelet surface than those in the control group." (PMID 40022154, 2025). "The homozygous mutations in ITGA2B or ITGB3 locus could cause Glanzmann thrombasthenia, a bleeding disorder." (PMID 34837956, 2021). "In this study we generated a patient-specific hiPSC-based model of Glanzmann thrombasthenia with compound heterozygosity of 2 novel mutations in the ITGA2B gene, which enabled the perpetual in vitro differentiation of GPIIbIIIa deficient platelets and MKs from hematopoietic precursors." (PMID 25607928, 2015). "One patient, who showed Glanzmann thrombasthenia-like marked reduction in surface αIIbβ3 expression (3–11% of normal control), was a compound heterozygote with ITGA2B p.Gly991Cys and a novel nonsense mutation, ITGA2B p.Arg422*." (PMID 24498605, 2013). "Interestingly, VITT02 exhibited the presence of two variants in genes encoding for integrin family members, such as ITGA2B, encoding for the integrin alpha-IIb and associated with Glanzmann thrombasthenia (OMIM 273800), and ITGAD, encoding for the integrin alpha-D." (PMID 39035772, 2024). "Glanzmann’s thrombasthenia, the most representative IPFD, results from ITGA2B or ITGB3 mutations that disrupt the αIIbβ3 integrin complex, producing severe mucocutaneous bleeding." (PMID 41301446, 2025).
Glanzmann thrombasthenia (continued). "In a recent study, Integrin Subunit Alpha 2b (ITGA2B), platelet and megakaryocytes transmembrane glycoprotein, involved in platelet aggregation and in thrombasthenia, was identified as NSCLC platelet RNA marker in a test and an independent validation cohort." (PMID 36046776, 2020). "Mutations in ITGA2B and ITGB3 cause Glanzmann thrombasthenia, an inherited bleeding disorder in which platelets fail to aggregate when stimulated." (PMID 24236036, 2013). "Encoded by the genes ITGA2B and ITGB3, mutations are associated with Glanzmann thrombasthenia (GT)." (PMID 27025194, 2016). "Therefore, we used Vivo morpholino and created an adult Glanzmann's thrombasthenia phenotype by knockdown of the itga2b (CD41) gene." (PMID 22778746, 2012).
COVID-19 (32 papers, 2020 to 2025). A disease caused by infection with severe acute respiratory syndrome coronavirus 2. "In the present study, ITGA2B and ITGB3 were identified as key genes for COVID-19-related stroke, and these biological processes were closely associated with COVID-19-related stroke." (PMID 35557984, 2022). "Of note, in diseases with a high risk of thrombosis, such as lung cancer and lupus anticoagulants, we have previously observed a decrease in the total ITGA2B level in the platelet proteome, but not to this extent, underlining the magnitude of thrombotic dysregulation in COVID-19." (PMID 34859078, 2021). "Most crucially, ITGA2B and ITGB3 were shown to be the hub genes for key stroke-related modules, suggesting that they play critical roles in COVID-19-related stroke." (PMID 35557984, 2022). "Therefore, platelet activation, ECM-receptor interaction, PI3K-Akt signaling pathway, and hematopoietic cell lineage may represent the potential biological processes associated with COVID-19-related stroke, and ITGA2B and ITGB3 may be potential intervention targets for COVID-19-related stroke." (PMID 35557984, 2022). "As a result, ITGA2B and ITGB3 have been identified as important genes involved in COVID-19-related stroke." (PMID 35557984, 2022). "Thus, in the case of reduced total ITGA2B amount in the platelets of COVID-19 patients, less PAC-1 binding signal may be detected compared to healthy controls, even during an increased activated state of the integrin-αIIbβ3 complex, and thus hypo-reactivity of the platelets may be concluded." (PMID 34859078, 2021). "ITGA2B and ITGB3 have been further identified as crucial genes of COVID-19-related stroke." (PMID 35557984, 2022). "In addition, ITGA2B and ITGB3 were obtained by crossing these common genes with the hub genes of stroke-related crucial module, suggesting that these two genes are more crucial than other common genes in the mechanisms of COVID-19-related stroke." (PMID 35557984, 2022). "An additional planned contrast analysis of the time course of ITGA2B levels in platelets further showed a significant decrease of ITGA2B over time in non-surviving COVID-19 patients, which fits to the decrease in the activated integrin-αIIbβ3 complex observed in non-survivors by flow cytometry." (PMID 34859078, 2021). "Additionally, ITGA2B and ITGB3 may be promising intervention targets for COVID-19-related stroke." (PMID 35557984, 2022). "Thus, the drop of the activated αIIbβ3 complex on platelets of non-surviving COVID-19 patients, observed in the current study, may be attributed to a generally declining amount of total ITGA2B in their platelets due to hyper-activation." (PMID 34859078, 2021). "In addition, using an unbiased platelet proteome analysis, we found that the total amount of one part of this integrin complex, ITGA2B, was decreased in all COVID-19 patients compared to healthy controls, and in non-survivors the decrease was even stronger after 4–5 days." (PMID 34859078, 2021).
Sepsis (23 papers, 2012 to 2025). Sepsis is defined as life-threatening organ dysfunction caused by a dysregulated host response to infection. "Its protein transcript, integrin Alpha 2B (ITGA2B), was increased in circulating platelets and associated with higher mortality of patients and mice with sepsis." (PMID 33369167, 2021). "Previous studies utilizing a sepsis mouse model demonstrated the upregulation of the ITGA2B gene, which correlated with increased mortality rates." (PMID 40243635, 2025). "KLF4 down‐regulation resulting from promotion by TLR4 of ERK1/2 phosphorylation leads to elevated ITGA2B expression, which underpins the inflammatory response in sepsis." (PMID 33369167, 2021). "The expression of ITGA2B was elevated approximately ninefold in platelets from patients with sepsis, but this aberrant expression resolves in patients who survive sepsis." (PMID 33369167, 2021). "Accordingly, ITGA2B merits study as the downstream of KLF4 in sepsis." (PMID 33369167, 2021). "During the current investigation, we aimed to prove the hypothesis that the TLR4/ERK1/2/KLF4/ITGA2B axis is capable of mediating inflammatory response of sepsis." (PMID 33369167, 2021). "Accordingly, we investigated further the role of the TLR4/ERK1/2/KLF4/ITGA2B axis in sepsis." (PMID 33369167, 2021). "To test this hypothesis, we established CLP‐induced septic mice and LPS‐induced RAW264.7 cells and characterized the role of the TLR4/ERK1/2/KLF4/ITGA2B axis in the setting of sepsis in vivo and in vitro." (PMID 33369167, 2021). "Herein, we investigate the hypothesis that the TLR4/ERK1/2/KLF4/ITGA2B axis mediates the inflammatory response of sepsis." (PMID 33369167, 2021). "ITGA2B was up‐regulated in the setting of sepsis and was inhibited by KLF4 overexpression." (PMID 33369167, 2021). "Very recently, ITGA2B (integrin subunit αIIb) expression has been found to be upregulated in circulating platelets during sepsis via dynamic trafficking of specific mRNA from MKs, and this was accompanied by increased production of integrin subunit αIIb and activation of integrin αIIbβ3." (PMID 32013235, 2020). "Hence, we thoroughly investigated LPS-induced transcriptional changes in MEG-01 cell cultures since increased ITGA2B mRNA content has been observed in MKs to be invested in platelets during sepsis." (PMID 32013235, 2020). "ITGB3 (integrin subunit beta 3) and ITGA2B (integrin subunit alpha 2 beta; both component chains of the heteromeric, platelet-specific integrin αIIbβ3), have also been the focus of intense interest in sepsis." (PMID 32318053, 2020). "To conclude, sepsis in mice could be alleviated by KLF4 through down‐regulation of ITGA2B." (PMID 33369167, 2021). "Collectively, these results explain the down‐regulation of KLF4 in sepsis, namely via TLR4 promotion of ERK1/2 phosphorylation, and identify ITGA2B as the downstream gene of KLF4, thus highlighting the anti‐inflammatory role of KLF4 in sepsis." (PMID 33369167, 2021). "Gene entities shared between sepsis and severe sepsis response hubs are; TDRD9 – LIN7A, GPR84 – ENTPD7, PYCT1A and ZDHHC19, CD177 – DDAH2 and RGL4, SLC16A3 – DENND3 and MBD6, MYL9 – CMTM5, ITGB3, ITGA2B, NRGN, SELP and TREML1." (PMID 32318053, 2020). "It interacts with TREML1, CMTM5, TGFB1l1, and ITGA2B in adult SIRS, among others and TGFB1l1 only in adult sepsis." (PMID 32318053, 2020).
Stroke (23 papers, 2010 to 2025). Sudden impairment of blood flow to a part of the brain due to occlusion or rupture of an artery to the brain. "VASP is an actin regulatory protein implicated in platelet adhesion while ITGA2B encodes aIIb and is an important gene associated with COVID-19-related stroke." (PMID 36859478, 2023). "The CytoHubba plug-in of the Cytoscape was utilized to visualize the genes of stroke-related crucial module, and the top five genes were selected as hub genes using EcCentricity as the ranking method (MPO, MMP9, ITGA2B, ITGB3, and RETN)." (PMID 35557984, 2022). "The platelet proteomic profiling data revealed that the differences in log2 ratio intensities between ITGA2B and ITGB3 levels of stroke patients and of those patients in the control group." (PMID 27336623, 2016).
thrombosis (18 papers, 2012 to 2023). "The decrease in ITGA2B and ITGB3 levels in platelets during this prothrombotic condition of patients with lung cancer and LA with thrombosis history may be caused by the continuous shedding of extracellular vesicles, which was recently also described as “membrane pearling” of platelet pseudopodia." (PMID 34066760, 2021).